CAMP (cathelicidin antimicrobial peptide)
Diseases named in the same sentence as CAMP in open-access papers (continued):
Sharing a sentence is not in itself a finding about the gene and the disease.
lung adenocarcinoma (3 papers, 2021 to 2022). A carcinoma that arises from the lung and is characterized by the presence of malignant glandular epithelial cells. "We found CD1A|CXCL13, CD1A|S100A7L2, IFNA7|CMTM2, IFNA7|CSF3, CAMP|TFR2, this 5‐IRGPs were strongly associated with the prognosis of patients, all of which were protective factors for the prognosis of lung adenocarcinoma." (PMID 35246970, 2022). "In the analyses of oncogenic gene sets, we found six gene sets (SINGH KRAS Dependency Signature, CAMP UP.V1 UP, MYC UP.V1 UP, RB P107 DN.V1 UP, E2F1 UP.V1 UP and CSR LATE UP.V1 UP) associated with lung adenocarcinoma." (PMID 33446784, 2021).
mastitis (3 papers, 2018 to 2022). Inflammation of breast tissue during lactation or postpartum due to an obstructed duct or infection. "Genes coding for proteins such as haptoglobin, cathelicidin antimicrobial peptide, and lingual antimicrobial peptide have been identified as potential biomarkers for mastitis detection." (PMID 31921295, 2019). "Genes coding for proteins such as Haptoglobin (HP), Serum Amyloid A (SAA), Cathelicidin antimicrobial peptide (CAMP), and Lingual antimicrobial peptide (LAP) have been identified as potential biomarkers for mastitis detection." (PMID 29470489, 2018).
neuroblastoma (3 papers, 2022 to 2024). Neuroblastoma (NB) is the most common solid, extracranial childhood tumor. "After exposure to 1 and the cAmp activator forskolin, the cAMP level in human neuroblastoma SK-N-SH changed, suggesting that the protease-resistant cyclic tetrapeptide is a potent MOR agonist with an EC50 of 2.5 nM." (PMID 38918367, 2024).
oral cancer (3 papers, 2017 to 2024). "Further studies would also be necessary to clarify functional role of CAMP/LL-37 in oral cancer cells." (PMID 28427192, 2017). "For instance, 5-azacytidine, a well-known DNMT inhibitor, increased CAMP and DEFB concentrations in gingival epithelial cells, oral carcinoma cells, keratinocytes, and chondrocytes." (PMID 39053604, 2024). "To determine the expression levels of human CAMP in the epithelial cancer cell, HaCaT cell, TR146 cell and human oral cancer cell HSC-3, HSC-4, we then performed qRT-PCR and western blot analysis." (PMID 28427192, 2017).
peritonitis (3 papers, 2014 to 2023). Inflammation of the peritoneum (tissue that lines the abdominal wall and covers most of the organs in the abdomen). "PD cells from patients with peritonitis (n = 3) showed higher baseline expression of CAMP (18-fold±9, p<0.05) and HAMP (64-fold±7) relative to cells from non-infected patients." (PMID 25549329, 2014). "This is consistent with previously reviewed responses to infection, and may be part of a program of peritoneal antibacterial responses, with CAMP also being induced (18-fold) in PD cells from patients with peritonitis." (PMID 25549329, 2014). "Expression of both CAMP (18.3-fold±9.4, p<0.01), and HAMP (64.1-fold±7.0, p<0.001) was increased in peritonitis PD cells from compared to non-infected patients." (PMID 25549329, 2014).
pertussis (3 papers, 2019 to 2025). A contagious bacterial respiratory infection caused by Bordetella pertussis. "Additionally, Escherichia coli, Shigella sonnei, and Salmonella enterica were positively correlated with the pathways of CAMP resistance, pertussis, lysosome, and sulfur metabolism." (PMID 34603257, 2021).
prion disease (3 papers, 2020 to 2026). A transmissible disease that is caused by a protein that is able to induce abnormal folding of normal cellular proteins, leading to characteristic spongiform brain changes, which are associated with neuronal loss without an inflammatory response. "The most relevant KEGG biological pathways included autophagy; the Rap1, CAMP, and ErbB signaling pathways; and additional neurogenerative diseases (i.e., Parkinson’s disease and prion disease)." (PMID 38469573, 2024).
Salmonella Infections (3 papers, 2012 to 2024). Infections with bacteria of the genus SALMONELLA. "After deleting the phoP gene, the down-regulated DEGs were mainly enriched in Salmonella infection, CAMP resistance and quorum sensing (padj < 0.05)." (PMID 38790833, 2024). "The Salmonella infection, cationic antimicrobial peptide (CAMP) resistance, quorum sensing and two-component system pathways were down-regulated, while the bacterial tricarboxylic acid cycle pathways were up-regulated." (PMID 38790833, 2024). "Generally, these DEGs are mainly enriched in two-component systems (TCS), Salmonella infection pathways, tricarboxylic acid (TCA) cycle, pyruvate metabolism, oxidative phosphorylation, and CAMP resistance pathways." (PMID 38738873, 2024).
vitamin D deficiency (3 papers, 2021 to 2022). A nutritional condition produced by a deficiency of VITAMIN D in the diet, insufficient production of vitamin D in the skin, inadequate absorption of vitamin D from the diet, or abnormal conversion of vitamin D to its bioactive metabolites. "This study examines the role of vitamin D deficiency in the regulation of Cathelicidin Antimicrobial Peptide (CAMP) in CD-like macrophages." (PMID 35444957, 2022). "Altogether, the data indicate that MAP infection and burden is significant in CD by disrupting the conversion of calcifediol to calcitriol and downregulation of CAMP expression leading to vitamin D deficiency." (PMID 35444957, 2022).
Candida infection (2 papers, 2011 to 2022). "Expression levels of CAMP were dramatically elevated in WT buccal tissue following Candida infection, and this induction was dependent on NLRC4, NLRP3 and ASC." (PMID 22174673, 2011).
depression (2 papers, 2020 to 2022). "KEGG results show that the mechanism of action of KXS in treating depression is through neural activity ligand-receptor interaction, the calcium signaling and CAMP signaling pathways." (PMID 36560929, 2022).
Hepatic steatosis (2 papers, 2021 to 2025). Steatosis is a term used to denote lipid accumulation within hepatocytes. "BAs bind to TGR5 to increase AHR expression and promote transcription of ACOX 1 and CPT 1 A by triggering CAMP-ERK pathway and inhibit NLRP3 activity by triggering CAMP-PKA pathway, while AHR also inhibit activation of NLRP3, thus inhibiting hepatic steatosis." (PMID 39944639, 2025).
hyper-IgE syndrome (2 papers, 2015 to 2016). A condition that is characterized by elevated serum IgE, dermatitis, and respiratory infections. "Next, the in vivo relevance of STAT3 in the regulation of the CAMP gene was investigated in immune cells from one patient with hyper-IgE syndrome (HIES)." (PMID 27633343, 2016).
Non-alcoholic fatty liver disease (2 papers, 2024 to 2026). "Other pathways include pathways in cancer (IL6 and AKT1), non-alcoholic fatty liver disease (AKT1 and IL1B), and the CAMP signaling pathway (AKT1)." (PMID 41601963, 2026).
Sciatica (2 papers, 2021). Pain in the lower back and hip radiating in the distribution of the sciatic nerve. "Combining these studies, a potential link between TLR4, MMP9, MPO, CAMP, RETN, and sciatica can be established, but microarray analysis showed that the expression of these genes was not changed after integrated TCM treatment." (PMID 33573686, 2021). "Network analysis identified TLR4, MMP9, MPO, CAMP, RETN and TLR5 as key genes contributing to the dysregulation of genes in the peripheral blood of patients with sciatica." (PMID 33535986, 2021). "Consistent with the microarray data, the expression levels of the key genes (TLR4, MMP9, MPO, CAMP, RETN and TLR5) were significantly increased in patients with sciatica compared with healthy controls." (PMID 33535986, 2021). "The PPI network suggested that TLR4, MMP9, MPO, CAMP, RETN, TLR5, and IL1RN were key genes in the dysregulation of genes in the peripheral blood of patients with sciatica." (PMID 33573686, 2021). "Bioinformatic analysis revealed that most of the DEGs-baseline were related to immunity and the inflammatory response and that TLR4, MMP9, MPO, CAMP, RETN, TLR5, and IL1RN were key genes involved in the dysregulation of genes in the peripheral blood of patients with sciatica." (PMID 33573686, 2021).
thymoma (2 papers, 2024 to 2025). A neoplasm arising from the epithelial cells of the thymus. "Two cycles of CAMP therapy resulted in sufficient tumor shrinkage to allow resection of only the upper division of the left lung along with resection of the thymoma, thereby avoiding lobectomy." (PMID 40959849, 2025).
ZIKV infection (2 papers, 2022 to 2024). "The results showed a significant decrease in the expression of vitamin D3 receptor (VDR), cytochrome P450 family 24 subfamily A member 1 (CYP24A1), and cathelicidin antimicrobial peptide (CAMP) genes upon ZIKV infection." (PMID 38839691, 2024). "The levels of CYP24A1 and CAMP mRNA were significantly lower at 12 and 48 hpi, two critical time points of ZIKV infection, in ZIKV-Mon and ZIKV-VitD3-Mon when compared to VitD3-Mon." (PMID 38839691, 2024). "Likewise, the inhibitory effect of ZIKV infection on CAMP expression was less pronounced in the presence of VitD3 at 12 hpi (p = 0.001 and 0.0178 respectively), but the levels of CAMP were similar at 48 hpi (p = 0.0021 and 0.0057, respectively)." (PMID 38839691, 2024). "Thus, a potential explanation for the inhibition of VDR and CAMP mRNA expression by ZIKV infection could involve the expression of innate immune receptors, such as TLR7 and TLR8, that recognize intracellular viral RNA." (PMID 38839691, 2024). "The effect of ZIKV infection on the VitD3 system of monocytes was investigated by determining the relative levels of expression of VDR, CYP24A1, and CAMP mRNA by RT-qPCR." (PMID 38839691, 2024). "The results show that ZIKV infection suppresses the expression of VDR, CYP24A1, and CAMP in monocytes, suggesting an alteration of the VitD3 signaling pathway." (PMID 38839691, 2024).
brain tumor (1 paper, 2025). "Moreover, the NE/CAMP+aPD‐1 combination treatment significantly suppressed brain tumor growth compared to the treatment with aPD‐1 alone, which led to a significant improvement in survival." (PMID 39801750, 2025).
cholera (1 paper, 2024). "For example, entinostat, a benzamide HDAC inhibitor, potently enhanced DEFB1 and CAMP mRNA expression in intestinal epithelial cells and protected rabbits from experimental cholera." (PMID 39053604, 2024).
cholestasis (1 paper, 2024). Impairment of the bile flow caused by obstruction within the liver, or outside the liver in the bile duct system. "Differences in the efficacy of CT_L and CF_L in treating cholestasis were found to be related to differences in the biosynthesis of unsaturated fatty acids, in ABC transporters and in CAMP signaling pathway." (PMID 38523644, 2024).
cutaneous leishmaniasis (1 paper, 2019). Leishmaniasis affecting the skin. "In the current study, we revealed the CAMP transcript to be strongly upregulated in skin lesion material from cutaneous leishmaniasis patients." (PMID 31824492, 2019). "In line, we identified a strong upregulation of the human CAMP mRNA transcript in clinical samples from African patients with cutaneous Leishmaniasis, suggesting cathelicidin to play a role in human CL in vivo." (PMID 31824492, 2019). "We found an increased expression of the human cathelicidin CAMP in skin lesions of Ethiopian patients with cutaneous leishmaniasis." (PMID 31824492, 2019). "We could demonstrate CAMP to be upregulated in lesion material from Ethiopian individuals suffering from cutaneous Leishmaniasis." (PMID 31824492, 2019).
diabetic foot ulcers (1 paper, 2025). "Similarly, in keratinocytes derived from diabetic foot ulcers, treatment with 1,25(OH)2D led to increased CAMP expression and LL-37 production, thereby promoting wound healing and antimicrobial activity." (PMID 39996823, 2025).
dry eye (1 paper, 2019). "Although these both genes were rarely reported to be associated with pSS, a study on experimental dry eye mouse model found CRAMP, the ortholog of human CAMP, was down regulated for mRNA and protein in the dry eye mouse." (PMID 31068931, 2019).
dyslipidemia (1 paper, 2021). "Furthermore, other studies showed that CAMP was related to dyslipidemia, indicating that CAMP might induce lipid abnormalities to increase the risk of AMI." (PMID 33603775, 2021).
gonococcal infection (1 paper, 2020). "Here, we show that gonococcal infection of human macrophages led to significant reduction in host defense CAMP genes expression encoding LL-37, HBD-1 and SLPI." (PMID 32085531, 2020). "To examine the mechanism of CAMP gene downregulation, we then investigated epigenetic modifications at the promoters of host defense genes of LL-37 and HBD-1 during gonococcal infection with WT and the Gc-HDAC-deficient isogenic mutant." (PMID 32085531, 2020).
H. pylori (1 paper, 2020). "H. pylori-infection, however, slightly enhanced CAMP expression at both the mRNA and protein levels in both WT and VDR-KD mice." (PMID 33194806, 2020).
infertile (1 paper, 2024). "Here, it is clear that CAMP is more abundant within the infertile samples." (PMID 39092172, 2024).
injury (1 paper, 2023). Damage inflicted on the body as the direct or indirect result of an external force, with or without disruption of structural continuity. "In this study, we investigated the effect of Hippophae rhamnoides L. (HRP) on the activity of CYP2D6 via the CAMP/PKA/NF-κB pathway in rats with Bacille Calmette–Guerin (BCG)-induced immunological liver injury." (PMID 37833431, 2023).
liver cancer (1 paper, 2023). An epithelial or non-epithelial malignant neoplasm that arises from the liver. "This implied that the decrease in CAMP protein in serum/circulating exosomes is partly owed to the decrease in CAMP in the liver cancer tissues and buffy coat in HCC." (PMID 37958632, 2023).
pharyngeal carcinoma (1 paper, 2021). "Similar to our findings, no cytotoxicity of S. pyogenes CAMP factor was observed in human pharyngeal carcinoma cells or murine macrophages." (PMID 34908468, 2021). "Additionally, S. pyogenes CAMP factor enhances adherence and invasion of human pharyngeal carcinoma cells in a serum-independent manner, but not human lung or keratinocyte cells." (PMID 34908468, 2021).
Respiratory tract infection (1 paper, 2018). An infection of the upper or lower respiratory tract. "In this study, we showed that infection with human metapneumovirus (hMPV), one of the leading causes of respiratory tract infections in young children, strongly suppressed basal and vitamin-D induced CAMP expression in human macrophages." (PMID 29780383, 2018).
ulcer (1 paper, 2014). "Intriguingly, previous studies by our group showed that most DFU patients showed not CAMP expression in biopsies from the ulcer, thus, these results may suggest that production of cathelicidin can be retrieved for DFU patients using 1,25(OH)2D3 treatment." (PMID 25337708, 2014).
vaginal candidiasis (1 paper, 2017). "We detected all isolates as Candida albicans and almost half of the isolates were CAMP-positive with S. aureus and S. agalactiae, suggesting that these bacteria increase the pathogenicity of Candida in vaginal candidiasis." (PMID 29318048, 2017).
viral ocular infections (1 paper, 2020). "Studies have shown that corneal and conjunctival epithelia express CAMP as part of mucosal innate immunity to protect against bacterial and viral ocular infections." (PMID 32867704, 2020).
infection (221 papers, 2005 to 2026). The state of being infected such as from the introduction of a foreign agent such as serum, vaccine, antigenic substance or organism. "Cathelicidin, encoded by CAP18/CAMP, has been shown to be involved in killing microbes, including Mtb, both in vitro and in vivo, and contributes to the host innate immune response to infection." (PMID 23448601, 2013). "To investigate the impact of reduced resistance of the graRS mutant to neutrophil and CAMP-mediated killing on the ability of the bacteria to cause infections in vivo, we compared the virulence of WT and mutant bacteria in a mouse challenge model." (PMID 18518949, 2008). "The increased susceptibility to infection by C. albicans in DEFB1−/− mice may also be explained by reduced induction of mucosal AMPs including cathelicidin antimicrobial peptides (CAMP), LL-37, mBD2, and mBD4." (PMID 35979535, 2022). "Based on these observations we postulated that vitamin D (25D)-deficiency associated with CKD may predispose to infection through impaired regulation of CAMP and HAMP activity." (PMID 25549329, 2014). "Treatment with calcifediol resulted in the reversal of these gene expression trends with an upregulation of CYP27B1 and VDR expression and downregulation of CAMP expression 24 h post-infection." (PMID 38732603, 2024). "MAP infection also resulted in an increased expression of CAMP 24 h post-infection relative to the control group with a mean fold change increase of 3.00 ± 0.08 (p-value < 0.001)." (PMID 38732603, 2024). "MAP infection was noted to exert the same upregulation effects on CYP27B1 and CAMP expression after 48 h of infection and treatment with SB 203580." (PMID 38732603, 2024). "Among these very heterogenous factors, adipose-derived Cathelicidin antimicrobial peptide (CAMP; also: LL37, CAP-18) has gained particular attention due to its crucial role in host defense against subdermal infection." (PMID 37629082, 2023). "Recent investigation has revealed the significant role of Cathelicidin antimicrobial peptide (CAMP) in infection defense and innate immunity processes in adipose tissue." (PMID 37629082, 2023). "CAMP is one of the inherent host barriers that the pathogens encounter during the course of infection." (PMID 37289068, 2023). "The concentrations of CAMP in serum from young and aged ferrets before and after infection were similar." (PMID 38169647, 2023). "CAMP induces immune cells to the site of injury or infection to bind and neutralize lipopolysaccharide (LPS), thereby promoting epithelialization and repair the injury." (PMID 35224064, 2022). "The results of several studies have demonstrated that the anti-infection role of VitD3 against M. tuberculosis is closely associated with VitD3/VDR-signal mediated antimicrobial responses and the production of CAMP." (PMID 33194806, 2020). "Transcriptome group 1 (CAMP, CD14, FN1, TREM1) encodes for proteins that relate to acute response to infection, in particular to the LPS/TLR4 signaling pathway." (PMID 32325790, 2020). "Cathelicidin (CAMP) gene was down-regulated in macrophages infected with A. salmonicida and those inoculated with formalin-killed A. salmonicida at 1, 2, and 6 h post-infection compared with time-matched PBS controls." (PMID 31231379, 2019). "Already 24 h post infection (early), assessment of CAMP gene expression showed Lm-infected hMDM1 to have a slightly increased CAMP expression (2.1 ± 1.8-fold), compared to the uninfected control (normalized to 1; dashed line)." (PMID 31824492, 2019). "Macrophages infected with A. salmonicida showed a significant down-regulation of CAMP 2 h post-infection compared to the cells inoculated with inactivated bacteria." (PMID 31231379, 2019). "In this study, we show for the first time that infection with hMPV strongly suppresses basal and vitamin-D induced CAMP expression in human macrophages." (PMID 29780383, 2018).